LY6E (lymphocyte antigen 6 family member E)
Diseases named in the same sentence as LY6E in open-access papers (continued):
Sharing a sentence is not in itself a finding about the gene and the disease.
cancer (continued). "Besides LY6A/LY6S, other LY6 family members have been suggested as close homologues of the murine Ly6a gene, such as LY6D, LY6E, LY6H and LY6K, which were implicated as biomarkers for poor cancer prognosis and are frequently amplified in human cancer." (PMID 39642167, 2025). "We analyzed the expression pattern of LY6E in various cancers." (PMID 35310607, 2022). "Hence, we aimed to evaluate the expression levels, prognostic value, biological functions, and immune effects of LY6E via pan-cancer and CRC analyses using multiple databases." (PMID 35310607, 2022). "More importantly, we suggest that it might be better to pay attention to the side effects affecting normal T cells when we exploit LY6E as a target for cancer therapy." (PMID 27589564, 2016). "Increased expression of Ly6D, Ly6E, Ly6H or Ly6K was observed in sub-set of cancer type." (PMID 26862846, 2016). "Moreover, MIEF1 and LY6E may mediate different signalling pathways to induce apoptosis in the corresponding cancer cells." (PMID 35222533, 2022). "LY6E belongs to the LY6 gene family, which represent novel biomarkers for poor cancer prognosis and play essential roles in cancer progression and immune escape." (PMID 35123499, 2022). "LY6E, MUC1, and FOS play important roles in immune escape and suppressive immune microenvironment in various types of cancers." (PMID 33144684, 2021). "The expression levels of JUN, SFN, HSPB1, and CD47 in cancer cells and the expression levels of KLRB1, CD48, GZMK, and LY6E in CD8+ T cells were consistent with the scRNA-seq results." (PMID 33083004, 2020). "Here, we identified LY6E as an activator of HIF-1 and revealed their mechanistic and functional links in malignant tumor growth." (PMID 27589564, 2016). "Moreover, they observed that LY6E is required for TGF-β signalling and facilitates immune evasion by upregulating PD-L1 on cancer cells, by recruiting regulatory T cells and dampening NK-cell activation." (PMID 39642167, 2025). "Albeit, the upregulated LY6E in children with ASD might have cancer-promoting effects, thereby offsetting the anti-cancer effects of the other three dysregulated genes." (PMID 36077244, 2022). "It has not yet been elucidated how LY6E expression levels are upregulated in some types of cancers." (PMID 27589564, 2016). "Based on the result that LY6E expression levels were inversely correlated with those of PTEN and with the poor overall survival of cancer patients, we hypothesized that expression levels of PTEN in malignant tumors should be correlated with the poor prognosis of cancer patients." (PMID 27589564, 2016). "The signal for LY6E and CD44 was opposite to their expression pattern in mouse at both the single-cell and metacell levels, suggesting that their expression in DCs subtypes may not be conserved between human and mouse or across cancer types." (PMID 35963997, 2022).
LY6E also shares sentences with these, for which no sentence is quoted: Chagas disease (2 papers); discoid lupus erythematosus (2); influenza (2); viral diseases (2); adenocarcinoma (1); autism (1); autism spectrum disorder (1); bacterial infections (1); breast tumor (1); cardiac disease (1); Cognitive impairment (1); Dengue hemorrhagic fever (1); dermatomyositis (1); dilated cardiomyopathy (1); epilepsy (1); epileptic seizures (1); esophageal squamous cell carcinoma (1); Fever (1); hypertriglyceridemia (1); Infertility (1); lung adenocarcinoma (1); Palmoplantar keratoderma (1); parasite (1); parasitemia (1); pituitary tumor (1); pleural malignant mesothelioma (1); primary Sjögren syndrome (1); renal cell carcinoma (1); renal papillary cell carcinoma (1); systemic sclerosis (1).